CYP4B1 (cytochrome P450 family 4 subfamily B member 1)
Description:
Catalyzes the omega- and (omega-1)-hydroxylation of saturated fatty acids and n-alkanes (By similarity). Also bioactivates xenobiotics such as the procarcinogen 3-methoxy-4-aminoazobenzene and the cyclic arylamines 2-aminofluorene and 2-aminoanthracene (By similarity). In addition, catalyzes O-dealkylation of 7-ethoxycoumarin (By similarity). Functions at the interface of xenobiotic and endobiotic metabolism, contributing both to fatty acid and hydrocarbon oxidation and to the bioactivation of diverse xenobiotics. Preferentially hydroxylates the terminal carbon (omega-hydroxylation) of medium-chain fatty acids (C8-C10), with regioselectivity decreasing as chain length increases. C8 fatty acids and C7 n-alkanes display optimal chain length for regioselective omega-hydroxylation, and n-alkanes (C7-C10) are generally turned over faster and with higher regioselectivity than the corresponding fatty acids. In addition to omega/omega-1 hydroxylation, also catalyzes alpha-, beta-, gamma- and delta-hydroxylation of mid-chain length fatty acids, whereas fatty alcohols of the same chain length are almost exclusively hydroxylated at the omega, omega-1 and omega-2 positions (By similarity).
Synonyms: CYPIVB1; P-450HP
Tractability: Small molecule: it belongs to a druggable protein family. Antibody: UniProt places it where antibodies can reach, with medium confidence. PROTAC: a small molecule that binds it is known.
Safety:
Unwanted effects reported when the protein is acted on. In parentheses: how it was acted on, where the effect was seen, and who reports it.
drug toxicity (source: ClinPGx)
Gene: Protein-coding gene on chromosome 1 (46,757,838 to 46,819,413, forward strand). Ensembl gene ENSG00000142973.
Subcellular location: Endoplasmic reticulum membrane; Microsome membrane
Subcellular location (Human Protein Atlas): Vesicles
Pathways (Reactome):
Metabolism: Eicosanoids; Fatty acids; Miscellaneous substrates; Synthesis of Leukotrienes (LT) and Eoxins (EX)
Gene Ontology:
Molecular function: medium-chain fatty acid omega-1 hydroxylase activity; medium-chain fatty acid omega-hydroxylase activity; monooxygenase activity; oxidoreductase activity, acting on paired donors, with incorporation or reduction of molecular oxygen, reduced flavin or flavoprotein as one donor, and incorporation of one atom of oxygen; oxygen binding; fatty acid omega-1 hydroxylase activity; heme binding; heterocyclic compound binding; iron ion binding; oxidoreductase activity, acting on paired donors, with incorporation or reduction of molecular oxygen
Biological process: fatty acid metabolic process; fatty acid oxidation; xenobiotic metabolic process; biphenyl metabolic process
Cellular component: endoplasmic reticulum membrane
Genetic constraint (gnomAD): Loss-of-function variants: 45 observed, 56.81 expected, observed/expected ratio (o/e) 0.79, 90% interval 0.62 to 1.02. The upper end of that interval is the gene's LOEUF score, 1.02, which puts it in group 4 of 6, group 1 being the genes least tolerant of losing a copy. Missense variants: 656 observed, 681.45 expected, observed/expected ratio (o/e) 0.96, 90% interval 0.9 to 1.03. Synonymous variants: 248 observed, 260.36 expected, observed/expected ratio (o/e) 0.95, 90% interval 0.86 to 1.06.
Homologues: Orthologues: chimpanzee CYP4B1 (98% identical), macaque CYP4B1 (96% identical), dog CYP4B1 (87% identical), rat Cyp4b1 (86% identical), mouse Cyp4b1 (85% identical), pig CYP4B1 (74% identical), rabbit CYP4B1 (73% identical), Drosophila melanogaster Cyp4s3 (33% identical), Drosophila melanogaster Cyp4c3 (32% identical), Drosophila melanogaster Cyp4d2 (31% identical), Caenorhabditis elegans cyp-31A2 (30% identical), Caenorhabditis elegans cyp-31A3 (30% identical), and 24 more. Paralogues in human: CYP4A11 (53% identical), CYP4A22 (51% identical), CYP4X1 (46% identical), CYP4F2 (44% identical), CYP4F3 (44% identical), CYP4Z1 (44% identical), CYP4F11 (43% identical), CYP4F8 (43% identical), CYP4F12 (42% identical), CYP4F22 (42% identical), CYP4V2 (33% identical), CYP19A1 (21% identical).
Diseases named in the same sentence as CYP4B1 in open-access papers:
CYP4B1 is named in the same sentence as 45 diseases in open-access papers, as found by Europe PMC text mining. Sharing a sentence is not in itself a finding about the gene and the disease. The quoted sentences say what the papers report.
lung carcinoma (11 papers, 2014 to 2025). "CYP4B1 was regarded as a prognostic biomarker and tumor suppressor for lung cancer (LC), and missense variants in CYP4B1 were correlated with LC susceptibility." (PMID 38672263, 2024). "In conclusion, our study aimed to investigate the association between CYP4B1 single nucleotide polymorphism (SNP) and susceptibility to lung cancer." (PMID 37950293, 2023). "The genotype GA of CYP4B1-rs2297810 was significantly associated with an increased risk of lung cancer in both overall and stratified analyses." (PMID 37950293, 2023). "In any case, this study is the first to explore the association of CYP4B1 gene polymorphism with lung cancer susceptibility in the Chinese Han population and has achieved positive results." (PMID 37950293, 2023). "Secondly, further design of functional validation tests will help to accurately understand the mechanism of three CYP4B1 gene polymorphisms in the occurrence and development of lung cancer." (PMID 37950293, 2023). "These indicate that CYP4B1-rsS2297810, -rs4646491, and -rs2297809 are potential genetic risk factors for lung cancer." (PMID 37950293, 2023). "Genotype GA of CYP4B1-rs2297810 is a risk factor for both female and male lung cancer." (PMID 37950293, 2023). "Similarly, genotype CT of CYP4B1-rs4646491 and genotype CT of CYP4B1-rs2297809 are also associated with an increased risk of lung cancer." (PMID 37950293, 2023). "CYP4B1-rs2297809 is associated with an increased risk of female lung cancer." (PMID 37950293, 2023). "Functional assays demonstrated that CYP4B1 suppresses lung cancer progression and mitigates pathological cardiac remodeling." (PMID 40924729, 2025). "Together, these findings not only establish 1p‐Enh as a critical upstream regulator of CYP4B1 but also reveal its dysregulation as a mechanistic link between heart failure and lung cancer pathogenesis." (PMID 40924729, 2025). "CYP4B1 was significantly downregulated in lung cancer patients, which was further confirmed by UALCAN online database analysis in this study." (PMID 37950293, 2023). "In any case, this study has laid a reliable theoretical foundation for the mechanism of CYP4B1 in the development of lung cancer." (PMID 37950293, 2023). "Several studies detected the mRNA expression level of CYP4B1 in lung cancer samples and its corresponding paraneoplastic samples." (PMID 35154287, 2022). "Especially, five lung cancer-related genes including CYP4B1, CHRDL1, SFTPC, SFTPB, and AGER were consistently downregulated in both LUAD and LUSC had a positive correlation with TMPRSS2, exhibited an opposite effect on the prognosis of LUAD and LUSC." (PMID 35082790, 2021). "Due to the potential role of CYP4B1 in fatty acid metabolism, the study will help to explore the molecular mechanism of the occurrence and development of lung cancer and then lay a theoretical foundation for targeted metabolic reprogramming to treat lung cancer." (PMID 37950293, 2023). "In recent years, research on CYP4B1 in cancer has attracted special attention, which may be due to its different expression in patients with various cancers, including lung cancer, compared with normal individuals." (PMID 37950293, 2023). "We also found that the three missense variants in CYP4B1 were significantly associated with an increased risk of lung cancer in non-smokers, while no positive results were found in smokers." (PMID 37950293, 2023). "Cytochrome P4504B1 (CYP4B1) expression was dramatically reduced in lung cancer." (PMID 36090899, 2022). "Although no significant results of CYP4B1-rs2297809 associated with lung cancer were found in the male population, the overall trend was that the presence of the CT genotype of CYP4B1-rs2297809 will also increase the risk of male lung cancer (OR > 1)." (PMID 37950293, 2023). "However, no studies have reported the association between CYP4B1 genetic polymorphism and lung cancer risk in the Chinese Han population." (PMID 37950293, 2023).
lung carcinoma (continued). "Re-engineering of the human CYP4B1 enzyme based on the rabbit homolog CYP4B1 yielded an efficient activator of 4-IPO in HepG2 human hepatoma cells, making it a candidate for liver and lung cancer therapy." (PMID 38860140, 2024). "Upregulation of CYP4B1 during AT2-to-AT1 TD is affected by a specific ligand Wnt3a, that plays an important role in in lung cancer." (PMID 31492143, 2019). "Thus, the expression level of CYP4B1 is closely related to lung cancer, but its regulation mechanism in lung cancer is still not clear." (PMID 37950293, 2023). "However, for CYP4B1, ARHGEF6 and FAM189A2, their function in lung cancer are rarely studied." (PMID 33129284, 2020).
lung adenocarcinoma (7 papers, 2021 to 2026). A carcinoma that arises from the lung and is characterized by the presence of malignant glandular epithelial cells. "High expression of KRT6A (HR = 1.125, 95%CI = 1.047–1.207) and FAM83A (HR = 1.288, 95%CI = 1.138–1.457) was associated with poor DSS of lung adenocarcinoma, while CYP4B1 had the opposite effect on lung adenocarcinoma." (PMID 37081097, 2023). "High expression of KRT6A (HR = 1.075, 95% CI = 1.017–1.137) and FAM83A (HR = 2.436, 95% CI = 1.522–3.898) were associated with poor PFI of KIRC, while CYP4B1 (HR = 0.874,95% CI = 0.819–0.934) had the opposite effect on lung adenocarcinoma." (PMID 37081097, 2023). "Previous studies have reported significantly decreased CYP4B1 expression in LC tissues, identifying it as both a prognostic biomarker and a potential therapeutic target, especially in lung adenocarcinoma." (PMID 40924729, 2025). "Firstly, in the analysis of overall survival (OS), FAM83A (p = 2.06e-07), KRT6A (p = 1.22e-07), and CYP4B1 (p = 6.72e-05) had the most significant effect on the overall survival of patients with lung adenocarcinoma." (PMID 37081097, 2023). "The expression levels of CYP4B1 (lung adenocarcinoma, bladder Urothelial Carcinoma, bladder urothelial carcinoma, and breast invasive carcinoma) showed a significant relationship with different subtypes of these cancers." (PMID 35807355, 2022). "ANXA8L1 (kidney renal papillary cell carcinoma) and CYP4B1 (lung adenocarcinoma and bladder urothelial carcinoma) were highly expressed at the early stage of these cancers, but PSMF1 was highly expressed in stage III stomach adenocarcinoma." (PMID 35807355, 2022). "Analysis of the TCGA lung adenocarcinoma (LUAD) cohort (n = 567) revealed that CYP4B1 was significantly overexpressed in tumor tissue compared to normal lung samples (p < 0.001), with high expression correlating with improved overall survival (HR = 0.64; p = 0.001)." (PMID 40723371, 2025). "Additionally, CYP4B1 was positively associated with immune checkpoints such as PD-1 and PD-L1; these findings suggest that CYP4B1 could serve as a favorable prognostic biomarker and holds predictive value in the context of immunotherapy for lung adenocarcinoma." (PMID 40723371, 2025). "Inhibit CYP4B1 can promote the occurrence of lung adenocarcinoma by preventing metabolism, enhancing DNA replication, and cell cycle activity; when the specific situation is unknown, it needs to be verified by experiments." (PMID 37081097, 2023). "High expression of KRT6A (HR = 1.108, 95%CI = 1.004–1.223) and FAM83A (HR = 1.227, 95%CI = 1.074–1.402) had a poor prognostic progression of BRCA and lung adenocarcinoma, while CYP4B1 had the opposite effect on lung adenocarcinoma (HR = 0.860, 95%CI = 0.778–0.950)." (PMID 37081097, 2023). "Moreover, smoking showed a significant relation with the expression of CYP4B1 in lung adenocarcinoma (all FDR p < 0.05)." (PMID 35807355, 2022). "Furthermore, ANXA8L1 (kidney renal papillary cell carcinoma), CYP4B1 (lung adenocarcinoma) and TNS4 (stomach adenocarcinoma) showed a significant relation with survival in these cancers." (PMID 35807355, 2022). "In this study, using data from The Cancer Genome Atlas (TCGA) project and the Gene Expression Omnibus (GEO) database, a secondary analysis was performed to explore the expression profile of CYP4B1, as well as its prognostic value in patients with lung adenocarcinoma (LUAD)." (PMID 33592039, 2021). "In addition, CYP4B1 may hold significance in the prognosis of lung adenocarcinoma and the progression of urothelial carcinoma." (PMID 39010027, 2024). "In the prognostic analysis of progression-free interval (PFI), CYP4B1 (p = 6.40e-05) and KRT6A (p = 0.0111) had the highest impact on PFI in patients with lung adenocarcinoma, and FAM83A had a higher impact on PFI in KIRC (p = 0.0002052)." (PMID 37081097, 2023).
lung adenocarcinoma (continued). "In the prognostic analysis of disease-specific survival (DSS), CYP4B1 (p = 0.000249), FAM83A (p = 5.69E-05), and KRT6A (p = 0.001235) had the highest effect on the disease-specific survival of lung adenocarcinoma patients." (PMID 37081097, 2023). "In the prognostic analysis of disease-free interval (DFI), CYP4B1 (p = 0.003) and FAM83A (p = 0.003) had the highest effect on the disease-free progression of lung adenocarcinoma, while KRT6A (p = 0.046) had a higher effect on BRCA." (PMID 37081097, 2023). "Interestingly, using OS, DSS, DFI, and PFI related univariate Cox regression analysis in various tumors, we found that FAM83A, CYP4B1, and KRT6A had the most significant impact on the survival and progression of lung adenocarcinoma." (PMID 37081097, 2023).
breast carcinoma (6 papers, 2014 to 2025). "High-throughput next generation sequencing revealed that the Homo sapiens CYP4B1 gene carries more than 1,000 SNPs located within exonic regions and that the presence of specific SNPs was even associated with an increased risk for lung and gastric cancer as well as breast cancer." (PMID 40577420, 2025). "On the other hand, breast cancer patients (n = 1100) with low CYP4B1 and CYP4F12 expression levels showed better cumulative survival, whereas patients with high CYP4F3 expression had better overall survival than their counterparts." (PMID 40723371, 2025). "Bioinformatics indicated that breast cancer is influenced by genes like CYP4B1, CYP4F12, and CYP4F3." (PMID 40723371, 2025). "Similarly, CYP4B1 could also be detected in breast and tumor breast tissues, with 76.9% or 84.6%, respectively, thus suggesting an increased risk of developing prostate or breast cancer with increased CYP4B1 expression." (PMID 36768362, 2023). "The CYP4B1, CYP4F12, and CYP4F3 overall survival (OS) analyses were retrieved using the TIMER2.0 web server in breast cancer." (PMID 40723371, 2025). "According to the breast cancer stage results, no significant expression level of CYP4B1 can be observed between stages 1–4 and control (normal tissue)." (PMID 40723371, 2025). "We found that expressions of certain CYP genes is correlated with node status (N stage) of breast cancer including CYP2A6 (p-value = 0.025), CYP2C8 (p-value = 0.035), CYP2D6 (p-value = 0.027), CYP2J2 (p-value = 0.036), CYP3A7 (p-value = 0.026), and CYP4B1 (p-value = 0.046)." (PMID 28684774, 2017). "This study emphasizes CYP4B1, CYP4F12, and CYP4F3 gene expression levels, presenting tumor versus normal tissue analysis, their expression adjusted by stages, their correlation with BRCA1, BRCA2, and ESR1, the estrogen receptor status, and the overall survival analysis in breast cancer patients." (PMID 40723371, 2025).
bladder cancer (5 papers, 2019 to 2023). "Genetic polymorphism analysis revealed that two allelic combinations, CYP4B1/*1/*2 and CYP4B1/*2/*2, are associated with an increased risk of bladder cancer in the Japanese population; however CYP4B1*2 results in an inactive enzyme." (PMID 36768362, 2023). "Some studies revealed the presence of CYP4B1 in bladder tissues, thus provoking studies on possible correlation with the risk of developing bladder cancer and hCYP4B1." (PMID 36768362, 2023). "A study in Japanese found that individuals with CYP4B1*1/*2 or *2/*2 genotypes had a 1.75-fold increased risk of bladder cancer." (PMID 35176049, 2022). "In a Japanese population, subjects carrying the CYP4B1*1/*2 or CYP4B1*2/*2 genotypes exhibited a 1.75-fold increased risk of bladder cancer." (PMID 33592039, 2021). "Since CYP4B1 is involved in the metabolism of pro-carcinogens, its association with bladder cancer was investigated in a Japanese population, and subjects carrying the CYP4B1*1/*2 or CYP4B1*2/*2 genotypes exhibited a 1.75-fold increased risk of bladder cancer." (PMID 31480463, 2019). "Both the CYP4B1 expression level and its genotype impact the risk of bladder cancer." (PMID 36768362, 2023). "CYP4B1 was reported as procarcinogen for some chemicals in bladder carcinoma, down-regulated in esophageal squamous cell carcinoma and up-regulated in breast tumors when comparing the surrounding healthy tissues." (PMID 31244774, 2019).
ovarian carcinoma (4 papers, 2014 to 2025). A malignant neoplasm originating from the surface ovarian epithelium. "In a study of ovarian cancer (OV), CYP4B1 was identified as a differentially expressed gene in patients with advanced ovarian carcinoma, with significantly lower levels in those who experienced relapse following curative treatment." (PMID 40723371, 2025). "In ovarian cancers, patients with recurrent serous ovarian cancer were found to have higher CYP4B1 mRNA than patients with cured ovarian cancer." (PMID 38001897, 2023). "In contrast, only 8.3% of patients with ovarian cancers displayed medium CYP4B1 protein expression." (PMID 38001897, 2023). "While this effect size is relatively modest, it is a robust measurement across several datasets, and suggests that CYP4B1 may provide insights into therapy for ovarian cancer patients tailored by subtype." (PMID 26961683, 2016). "Similarly, three other genes, namely, CYP4B1, CEPT1, and CHMP4A are differentially regulated in patients who suffer from recurrent ovarian cancer disease." (PMID 27382614, 2014). "Another recent study integrated TCGA data and validated three genes (CYP4B1, CEPT1, and CHMP4A) in HGS-OvCa from patients likely to be cured by initial cytoreductive surgery and adjuvant chemotherapy; the precise role of these genes in ovarian cancer pathophysiology remains to be elucidated." (PMID 27382614, 2014).
bladder tumor (3 papers, 2019 to 2023). "One example is that a high expression of CYP4B1 increases the risk of bladder tumor by activation of 2-AF." (PMID 33592039, 2021). "Thereupon, CYP4B1 expression in the non-bladder tumor tissue appeared to be lower compared to its expression in bladder tumor samples." (PMID 36768362, 2023). "CYP4B1 is a cytochrome enzyme, which has been found to be highly expressed in bladder tumor patients." (PMID 31160636, 2019). "However, the expression of CYP4B1 in the human bladder exhibited high variation, whereby not only inter-individual but also differences between non-bladder tumor and bladder tumor tissues were noted." (PMID 36768362, 2023).
urothelial carcinoma (3 papers, 2019 to 2024). A malignant neoplasm derived from the transitional epithelium of the urinary tract (urinary bladder, ureter, urethra, or renal pelvis). "Downregulation of CYP4B1 proteins represented an unfavorable indicator in patients with urothelial carcinomas of the upper urinary tract and bladder, indicating a protective role of CYP4B1 in patients with urotherial carcinomas." (PMID 31480463, 2019). "Moreover, downregulation of CYP4B1 protein levels in urothelial carcinomas (UC) was found to be correlated with several clinicopathological factors of an advanced primary tumor, nodal metastasis, high histological grade, vascular invasion, perineural invasion, and mitotic rate." (PMID 33592039, 2021).